LIN28B (lin-28 RNA binding posttranscriptional regulator B)
Diseases named in the same sentence as LIN28B in open-access papers (continued):
Sharing a sentence is not in itself a finding about the gene and the disease.
hepatoblastoma (15 papers, 2016 to 2025). Hepatoblastoma (HB) is a malignant hepatic tumor and is the most common pediatric liver cancer. "Hepatoblastomas with high expression levels of stem/progenitor cell markers (EpCAM, LIN28B, SALL4, HMGA2, AFP) are usually associated with poor prognosis." (PMID 37414763, 2023). "In a murine model, LIN28B overexpression in hepatocytes was sufficient to cause hepatoblastoma but only when LIN28B was induced throughout the developmental stage." (PMID 34548635, 2022). "To detect the association between LIN28B gene polymorphisms and hepatoblastoma risk in Chinese children, we conducted a five-center case-control study of 275 hepatoblastoma patients and 1018 cancer-free controls." (PMID 32284747, 2020). "In this study, we did a five-center case-control study to investigate the association between LIN28B gene polymorphisms and hepatoblastoma susceptibility in Chinese Han children." (PMID 32284747, 2020). "Therefore, it was reasonable to investigate the genetic implication of the LIN28B gene in the risk of hepatoblastoma." (PMID 32284747, 2020). "LIN28B might also increase the risk of hepatoblastoma through LIN28B-RAN-AURKA pathway." (PMID 32284747, 2020). "In vertebrates there are two LIN28 paralogs, LIN28A and LIN28B, which are aberrantly expressed in numerous human cancers, including T-cell lymphoma, neuroblastoma, breast cancer, and hepatoblastoma." (PMID 38612395, 2024). "Similar examples have been shown in mouse models, where Lin28b overexpression can drive hepatoblastoma and hepatocellular carcinoma in the liver and neuroblastoma in the neural crest." (PMID 31616462, 2019). "Indeed, administration of let-7 prevents tumor formation in a mouse model of non-small-cell lung cancer (NSCLC) and LIN28B knockout and knockdown effectively upregulate let-7 levels and curb Wilms tumors and hepatoblastomas in mice." (PMID 38612395, 2024). "enrolled 275 hepatoblastoma cases and 1,018 healthy controls to prove LIN28B SNPs (rs94904590 T>G and rs314276 C>A) could increase the risk of hepatoblastoma." (PMID 34367972, 2021). "The previous study showed that lin-28 homolog B (LIN28B) might play a role in the development of hepatoblastoma." (PMID 32284747, 2020). "Finally, functional experiments should be performed to further explore the role of LIN28B in the carcinogenesis of hepatoblastoma." (PMID 32284747, 2020). "Meanwhile, LIN28B and AURKA expressions were upregulated in a transcriptomic and genomic analysis of human hepatoblastoma, and miRNA-26-5p inhibited hepatoblastoma by repressing LIN28B44." (PMID 32284747, 2020). "We first performed a transcriptomic evaluation of the two well‐recognized hepatoblastoma cell lines, HepG2 and HUH6, using Pearson's analysis with gene signatures in the public GSE168997 dataset to elucidate IGF2′′s role in hepatoblastoma (AFP, DUSP9, GPC3, DLK1, MYC, EPCAM, KRT8, and LIN28B)." (PMID 40271711, 2025). "We previously found that the deletion of Lin28a and Lin28b impaired the growth of MYC-induced pediatric hepatoblastomas in vivo, but the absence of Lin28a/Lin28b did not completely eliminate their initiation, possibly due to the high levels of MYC overexpression in that model." (PMID 38875287, 2024).
gastric cancer (13 papers, 2015 to 2025). A primary or metastatic malignant neoplasm involving the stomach. "We found that Lin28b expression was increased in gastric cancer tissues and was negatively associated with that of miR-498." (PMID 29970131, 2018). "UFC1 exerted its oncogenic activities in gastric cancer by sponging miR-498 and derepressing its downstream target Lin28b." (PMID 29970131, 2018). "Additionally, emerging evidence indicates that LIN28B promotes oncogenesis in gallbladder carcinoma, gastric carcinoma, and multiple myeloma via MYC transcriptional activation." (PMID 40740861, 2025). "Similarly, lower DNA methylation at four CpG sites has been observed at the LIN28B promoter in gastric cancer, leading to higher LIN28B expression and increased proliferation and migration." (PMID 37370851, 2023). "Studies on breast and gastric cancer have shown that RNA binding proteins such as PUM2 and Lin28B can bind to NRP1 mRNA, increasing its stability and expression, thereby affecting protein levels." (PMID 40806445, 2025). "Consistently, human AFP-producing gastric cancers often co-express pluripotency-related proteins, such as SALL4, LIN28A, and LIN28B." (PMID 29802314, 2018). "We found that AFP, LIN28B, and SALL4 were overexpressed in seven, eight, and nine cases of the 200 human gastric cancers, respectively." (PMID 29802314, 2018). "Twenty-five gastric cancers that were diagnosed as AFP-producing gastric cancers, were examined for the expression of SALL4, LIN28A, and LIN28B by immunostaining." (PMID 29802314, 2018). "In gastric cancer, NRP1 expression confers cancer stemness with binding to Lin28B." (PMID 32408477, 2020). "Notably, as observed in gastric cancers in KC-OSKM mice, SALL4, LIN28A, and LIN28B were frequently co-expressed in human AFP-producing gastric cancers, suggesting that these cancers exhibit activation of the pluripotency-related regulatory network." (PMID 29802314, 2018). "On the contrary, Lin28b knockdown reversed the promoting role of UFC1 in gastric cancer progression, suggesting that the upregulation of Lin28b contributes, at least in part, to the oncogenic role of UFC1 in gastric cancer." (PMID 29970131, 2018). "Moreover, the expression level of Lin28b was significantly upregulated in gastric cancer tissues and gastric cancer cell lines compared to non-tumor tissues and normal gastric mucosa epithelial cell line, respectively." (PMID 29970131, 2018).
leukemia (13 papers, 2016 to 2025). A malignant (clonal) hematologic disorder, involving hematopoietic stem cells and characterized by the presence of primitive or atypical myeloid or lymphoid cells in the bone marrow and the blood. "Lin28b promotes a substantial increase in lipid content, upon which the survival of Rpl22-deficient leukemias depends." (PMID 41389200, 2025). "In humans, high LIN28B expression is associated with juvenile myelomonocytic leukemias and specific subtypes of pediatric leukemias." (PMID 39478867, 2024). "Bulk-transduced populations were transplanted into recipient mice to generate primary murine leukemias and determine if coexpression of Plag1 or Lin28b would phenocopy Ezh2 loss and accelerate AML onset in comparison with MLL-AF9 alone." (PMID 30890554, 2019). "Overexpression of LIN28B has been associated with advance human malignancies, including leukemias, and there are increasing evidences of its role in formation of CSCs and LSCs through either let-7 dependent or independent mechanisms." (PMID 28693523, 2017). "Instead, we identified induction of the stemness factor Lin28b in the resulting leukemias, which is a key driver of the enhanced lipid synthesis (TG) that supports Rpl22-deficient leukemia survival." (PMID 41389200, 2025). "Altogether, our data establish two key points about the role of Lin28b in MLLr leukemia suppression." (PMID 38321106, 2024). "Although LIN28B has predominantly been reported to have a pro-leukemic role in AML, one study on a murine KMT2A::MLLT3 AML model suggests that LIN28B abrogates perinatal leukemia development." (PMID 38601080, 2024). "We performed LIN28 co-IP and mass spectrometry (MS) on lysates from embryonic stem cells and leukemia cell lines with high levels of LIN28A or LIN28B expression." (PMID 38875287, 2024). "Experimentally lowered DNA methylation of the AluJb promoter increases AluJb-LIN28B fusion protein expression and higher DNA methylation reduces its expression in leukemia cells." (PMID 37370851, 2023). "TF-1a AML cell line, a more immature and aggressive phenotype of leukemia, shows increased LIN28B expression." (PMID 28693523, 2017). "Our findings provide an advanced knowledge of LIN28B regulatory network in malignant hematopoiesis, as well as leukemia stem cell, thus providing a novel drug target for cancer therapy." (PMID 28693523, 2017). "This is consistent with previous reports showing an association of Lin28B with malignant tumors and miR-150 repression in MLL leukemias." (PMID 27007052, 2016). "Indeed, Lin28b knockdown reduced triacylglycerol (TG) synthesis preferentially in Rpl22−/− leukemias." (PMID 41389200, 2025). "While we did not observe induced mRNA encoding SREBP-1 in Rpl22−/− leukemias, this is not surprising since their regulation by Lin28b is post-transcriptional." (PMID 41389200, 2025). "LIN28B is frequently aberrantly expressed in cancers, including leukemia." (PMID 38601080, 2024). "However, modulation of another Lin28B target, let-7g, was most correlative with leukemia disease latency." (PMID 27007052, 2016). "Altogether, these findings reveal that Rpl22 insufficiency enhances the leukemia potential of HSCs through regulation of FAO and promotes leukemogenesis through Lin28b promotion of lipid synthesis." (PMID 41389200, 2025). "Further, the miRNA regulator protein and c-Myc target gene, Lin28B, is increased in MLL leukemia cells compared to bone marrow." (PMID 27007052, 2016). "While miR-150 is repressed uniformly across MLL subtypes, let-7g is differentially repressed by Lin28B according to expression level, which reinforces high c-Myc expression in MLL leukemias with short disease latency." (PMID 27007052, 2016). "A possible negative outcome of Lin28b induction into adult HSCs is the potential for developing leukemia, as Lin28 is highly expressed in some pediatric leukemias." (PMID 40143971, 2025).
leukemia (continued). "First, they show that Lin28b is not the sole effector of fetal leukemia suppression, given that Lin28b deletion did not accelerate AML initiation following fetal MLL::ENL induction." (PMID 38321106, 2024). "The expression of oncogenes such as LIN28B in fetal HSPC, may therefore play a role in leukemia initiation and transformation of fetal target cells, and in particular the development of aggressive leukemias in infancy and early childhood." (PMID 33679795, 2021). "Irrespective of the gestational origin of the leukemia-initiating cell, Rpl22 deficiency cooperates with MLL-AF9 to lead to both Lin28b induction and the disabling of the recently reported tumor-suppressive activity of Lin28b in postnatal MLL-based leukemogenesis." (PMID 41389200, 2025). "However, oncofetal RBPs such as LIN28B and IGF2BP3 allow specific targeting in MLL-r leukemia cells and, thus, could be particularly valuable therapeutically." (PMID 36307883, 2022). "This is perhaps not surprising because Lin28b is primarily expressed in fetal progenitors, but it does raise the possibility that the progenitor population for the resulting Rpl22-deficient MLL-AF9 transgenic leukemias may be of fetal origin." (PMID 41389200, 2025). "Given >50% of human neonatal leukemias are of myeloid lineage, these findings seem counterintuitive, although it is possible that neonatal AML arises from LIN28B negative progenitors." (PMID 38601080, 2024). "To exclude nonspecific effect, we overexpressed LIN28B in TF-1 and HEK293T cells, a non-leukemia cell line." (PMID 28693523, 2017). "Moreover, neither expression of Plag1 nor Lin28b was significantly altered following GSK343 treatment of MLL-AF9 tumors, reinforcing the concept of disparity between transcriptional programs repressed by Ezh2 that are responsible for early tumor suppression and later maintenance of these leukemias." (PMID 30890554, 2019).
colorectal cancer (11 papers, 2013 to 2025). A primary or metastatic malignant neoplasm that affects the colon or rectum. "The RNA-binding protein LIN28B is overexpressed in over 30% of patients with colorectal cancer (CRC) and is associated with poor prognosis." (PMID 37318881, 2023). "Claudin 1 TJ protein has been recently reported to mediate RNA-binding protein LIN28B to promote invasion and liver metastasis of colorectal cancer." (PMID 37611445, 2023). "Studies demonstrated that Insulin receptor substrate 1 (IRS1) promoted tumor growth in colorectal cancer targeted by miR-30a-5p and was stabilized by RNA-bindingprotein lin-28 homolog B (LIN28B)." (PMID 34488531, 2021). "To further confirm this interesting observation, we characterized that Lin28b known as a suppressor for Let-7 miRNAs is regulated by Fhit gene in lung cancer or colorectal cancer cell line." (PMID 33437205, 2021). "LIN28B overexpression activates the PI3K/AKT pathway in colorectal cancer, promoting metastasis." (PMID 39808497, 2025). "Lin28B could be detected in the ovarian, hepatic, and colorectal cancer cell lines." (PMID 24244607, 2013). "Apart from its role in colorectal cancer (CRC) initiation and progression, there is some evidence that LIN28B might promote CRC differentiation." (PMID 33755595, 2021). "To further confirm the Fhit-dependent miR-20a/b regulation, we analyzed the endogenous expression of both Lin28A and Lin28B expression, and found that Lin28B is abundant in A549 and H1299 lung cancer cells and HEK293 cell compared to HCT116 colorectal cancer cell." (PMID 33437205, 2021).
liver cancer (10 papers, 2017 to 2025). An epithelial or non-epithelial malignant neoplasm that arises from the liver. "We then introduced the same reporters into SNU308, a liver cancer cell line with little LIN28B expression." (PMID 38875287, 2024). "More importantly, a single RBP, such as LIN28B, can initiate the occurrence of liver cancer, indicating that RBPs dysregulation are significant driving factors in cancer development." (PMID 39267787, 2024). "IMP3 is also required in the context of the LIN28B overexpression that drives liver cancer in murine models." (PMID 34154626, 2021). "More importantly, Lin28b has been shown as sufficient to drive liver cancer and necessary for cancer maintenance in murine models." (PMID 32668728, 2020). "To distinguish among these, we performed LIN28B loss- and gain-of-function experiments in 2 human liver cancer cell lines that do and do not express LIN28B (Huh7 and SNU308, respectively)." (PMID 38875287, 2024). "Many human liver cancers are characterized by LIN28B overexpression." (PMID 28400788, 2017). "Similarly, Lin28b deletion extended survival in another liver cancer mouse model, LAP-MYC." (PMID 28400788, 2017). "Recent evidence has revealed that LIN28B is a key oncofetal RBP and is sufficient to drive hepatocarcinogenesis 15, suggesting the importance of RBPs in building the oncofetal system of liver cancer cells." (PMID 39267787, 2024). "For example, LIN28A and LIN28B regulate the expression of genes, such as the transcription factor SREBP1, which is involved in the regulation of fatty acid synthesis, thus enhancing lipid accumulation and de novo fatty acid synthesis in liver cancer cells." (PMID 40265419, 2025). "In addition to the classic oncofetal gene of LIN28B, we also found a more specific RBP, TRIM71, which is one of the top enriched genes in oncofetal liver cancer cells." (PMID 39267787, 2024). "Lin28b is a miR-125a target gene that, when downregulated, can inhibit liver cancer cell proliferation, NR0B1 (also called DAX-1) can inhibit the proliferation of liver cancer cells by suppressing the transcriptional activity of β-catenin." (PMID 33228611, 2020).
medulloblastoma (8 papers, 2015 to 2025). A malignant, invasive embryonal neoplasm arising from the cerebellum. "Additional studies will help further evaluate the cause of LIN28B upregulation in medulloblastoma." (PMID 37341142, 2023). "We are also exploring additional roles of LIN28B including in regulating metastasis as well as the roles of its other downstream targets in medulloblastoma." (PMID 37341142, 2023). "In this study, we demonstrate LIN28B's essential role for Group 3 medulloblastoma cell proliferation and reveal the LIN28B–let‐7–PBK axis as a major pathway exploited by these cancer cells." (PMID 37341142, 2023). "Overexpression of LIN28B in Group 3 medulloblastoma cells promotes the upregulation of PBK and other oncogenes via inhibition of the microRNA let‐7." (PMID 37341142, 2023). "In this context, a notable example is given by the miRNA-processing gene LIN28B, whose promoter is hypomethylated in all Group 3 and 4 medulloblastomas with increased LIN28B expression, and consequent downregulation of the tumor-suppressive LET-7 miRNA family." (PMID 30279357, 2018). "A recent whole-genome methylation profiling analysis, however, did find a hypomethylation in an alternative promoter of LIN28B that was correlated with increased LIN28B expression particularly in Group 3 and Group 4 medulloblastomas." (PMID 28186969, 2017). "LIN28B is highly expressed in AT/RT compared with medulloblastoma and other embryonal tumors, whereas primary let-7g miRNA is down-regulated." (PMID 27095948, 2016). "LIN28B expression is a poor prognostic factor in medulloblastoma, LIN28A is associated with worse prognosis in primitive neuro-ectodermal tumor, and LIN28A and LIN28B are known to be expressed in germ cell tumors." (PMID 25638158, 2015). "By qPCR we found increased LIN28B expression in 16/31 (52%) of medulloblastoma samples, compared to normal pediatric cerebellum." (PMID 25638158, 2015). "LIN28B is expressed in a poor-prognosis subset of medulloblastoma, and a subtype of primitive neuroectodermal tumors has increased expression of LIN28A." (PMID 25638158, 2015). "Interestingly, the knockdown of SMARCB1 in glioblastoma and medulloblastoma generated little effect on the LIN28B levels and the expression of CCND1 and CDKN1C." (PMID 27095948, 2016). "This is consistent with previous reports of increased LIN28B expression in medulloblastoma." (PMID 25638158, 2015). "However, the specific role of the LIN28B protein in medulloblastoma remains unexplored." (PMID 40265419, 2025). "Previous independent studies have shown an intriguing abnormal expression of the pluripotency-related genes POU5F1/OCT4, LIN28B, SOX2 and L1TD1, in medulloblastoma." (PMID 28186969, 2017). "Taken together, our data support the hypothesis that LIN28B and its downstream target PBK are important regulators of Group 3 medulloblastoma cell proliferation and that targeting the LIN28B–PBK axis with pharmacologic therapy is plausible." (PMID 37341142, 2023).